OLFM4 (olfactomedin 4)
Diseases named in the same sentence as OLFM4 in open-access papers (continued):
Sharing a sentence is not in itself a finding about the gene and the disease.
prostate carcinoma (continued). "Collectively, these results suggest that the expression of OLFM4 in human prostate-cancer cell lines that normally lack OLFM4 expression inhibits the hedgehog-signaling pathway." (PMID 26581960, 2015). "Our previous findings have strongly suggested that OLFM4 plays a critical role in regulating progression of human prostate cancer." (PMID 26581960, 2015). "Further, our functional studies of OLFM4 in human prostate-cancer cells have demonstrated that restoration of OLFM4 expression in the metastatic prostate-cancer cell line PC-3 significantly inhibited cancer-cell growth, invasion, and metastasis." (PMID 26581960, 2015). "Bioinformatic analyses revealed that expression of OLFM4 was significantly downregulated in advanced human prostate cancer." (PMID 26581960, 2015). "Overexpression of OLFM4 has been shown to facilitate mouse prostate tumor Tramp-C1 cells growth in syngeneic C57/BL6 mice but inhibit human prostate cancer PC-3 cell proliferation." (PMID 22471589, 2012). "In particular, H2O2-induced cellular apoptosis was attenuated by overexpressed OLFM4 in a prostatic cancer cell line." (PMID 22471589, 2012). "The absence of OLFM4 gene expression is associated with the progression of human prostate cancer, but its role and the molecular mechanisms involved in this process have not been completely understood." (PMID 35327169, 2022). "Thus, the Olfm4 gene seems to serve as a tumor suppressor in the progression of prostate cancer and other tumors." (PMID 26581960, 2015). "In addition, AR-positive, androgen-sensitive VCaP prostate-cancer cells transiently overexpressing OLFM4 displayed reduced expression of SHH and GLI at the mRNA level but not the protein level." (PMID 26581960, 2015). "We have previously verified that human metastatic prostate-cancer cells lack OLFM4 expression." (PMID 26581960, 2015). "In addition, OLFM4 has been reported inhibitory to the growth and metastasis of prostate cancer 19 and malignant melanoma 20, suggesting that the behaviour of OLFM4 is tissue specific or cancer type specific." (PMID 26416558, 2015). "Therefore, OLFM4-expressing stem/progenitor cells may be targets of oncogenic transformation in the progression of prostate cancers." (PMID 33318499, 2020). "We detected positive OLFM4 staining, but not SHH staining, in Gleason score 4–7 prostate-cancer specimens, while OLFM4 staining was reduced or lost and SHH staining was increased in Gleason scores 8–10 prostate-cancer specimens." (PMID 26581960, 2015). "The percentage of OLFM4- and SHH-positive prostate-cancer specimens was 80% and 40% in Gleason scores 4–7, and 22% and 57% in Gleason scores 8–10, respectively." (PMID 26581960, 2015). "OLFM4 interacts with GRIM-19, which is a component of the respiratory complex I of mitochondria with an anti-apoptotic role in prostate cancer cells." (PMID 26561938, 2015). "The expression of OLFM4 and SHH proteins was examined in prostate-cancer tissue-array samples using immunohistochemistry." (PMID 26581960, 2015). "OLFM4 is a glycoprotein for which the absence of gene expression has been shown in human prostate cancer." (PMID 37834239, 2023). "In this study, we observed that restoration of OLFM4 in human metastatic prostate-cancer cell lines lacking expression of OLFM4 inhibited hedgehog-signaling activity." (PMID 26581960, 2015). "To study whether OLFM4 protein directly inhibits hedgehog signaling-pathway activity, we performed GLI-reporter activity assays with human prostate-cancer cells." (PMID 26581960, 2015).
Obesity (14 papers, 2015 to 2025). Accumulation of substantial excess body fat. "A transcriptome–metabolome analysis of blood from breast cancer patients with obesity revealed more than 180 differentially expressed genes and nearly 100 metabolites; notably, OLFM4 expression was markedly elevated in the obese subgroup." (PMID 41303351, 2025). "Seven SNPs were also associated with obesity in Central Mexican children (SEC16B rs543874, OLFM4 rs12429545, rs9568856, FTO rs9939609, MC4R rs6567160, GNPDA23 rs1330484, and LMX1B rs3829849)." (PMID 31936053, 2020). "Hence, we cannot definitively conclude that OLFM4 in the jejunum is involved in gut dysbiosis-related inflammation because our patients presented low-grade chronic inflammation due to obesity, but it would be interesting to evaluate OLFM4 jejunal abundance in lean subjects." (PMID 35806447, 2022). "Therefore, the OLFM4 was upregulated in blood immune cells in obesity with BC, suggesting that it may play a unique role in immune cells and associated with increased risk of BC." (PMID 32509585, 2020). "Many of the upregulated immature neutrophil genes (e.g., OLFM4, DEFA1, ELANE, CEACAM6, CEACAM8, CTSG) have been found to be differentially expressed in persons with obesity and type 2 diabetes, both common comorbidities with psychotic disorders." (PMID 37147304, 2023). "In this sense, given that OLFMs are strongly linked to cellular processes and have been related to some disorders, such as obesity and hepatocarcinoma (HCC), among others, we wanted to evaluate the possible roles of OLFM2 and OLFM4 in NAFLD pathogenesis." (PMID 35806447, 2022). "Examples of genome-wide significant age-associated sites include CpG loci located in the promoter region of the obesity gene LEP, the childhood obesity gene OLFM4, the T2D gene IRS2, and the newly identified MetS gene TFAP2B." (PMID 25806089, 2015). "Other biological mechanisms, such as neuroendocrine changes in the leptin-melanocortin pathway and overlapping genetic variation (e.g., OLFM4 and NEGR1), could also explain the correlation between obesity and depression." (PMID 37621933, 2023).
colon carcinoma (13 papers, 2010 to 2023). "Association of OLFM4 with tumour differentiation has been reported in gastric and colon cancers." (PMID 24495253, 2014). "OLFM4 inhibits colon cancer progression as a negative regulator of the WNT/β-catenin signalling pathway." (PMID 36690709, 2023). "In human patients, the expression level of OLFM4 is upregulated in early stage colon cancer, but is reduced or lost in advanced-colon cancer." (PMID 33490652, 2021). "Olfactomedin 4 immunostaining frequency or expression level is decreased in advanced gastric and colon cancers, indicating that OLFM4 is a valuable marker for prognosis of gastrointestinal tumours." (PMID 24495253, 2014). "Interestingly, we previously found that OLFM4 is a Wnt-signaling target gene and negatively regulates the Wnt-signaling pathway through directly binding to frizzled-7 and frizzled-10 in colon-cancer cells." (PMID 33318499, 2020). "Other reports implicate OLFM4 expression in tumour growth and, more specifically, in colon cancer." (PMID 20941359, 2010). "MIR34A expression resulted in downregulation of the stemness factors BMI1 proto-oncogene polycomb ring finger (BMI1), CD44, CD133, olfactomedin 4 (OLFM4), and MYC proto-oncogene bHLH transcription factor (MYC) in a colon cancer cell line, clearly connecting this axis to stemness." (PMID 38009093, 2023). "Expression of OLFM4 is low or absent in poorly differentiated or undifferentiated gastric and colon cancers and enhanced in more differentiated cancers." (PMID 24495253, 2014). "However, OLFM4 over-expression was shown to decrease cell adhesion and migration but not to alter proliferation of human colon carcinoma (HT-29) cells." (PMID 24495253, 2014). "In addition, in another public transcript data set (GSE76342) for the colon cancer cell line LoVo with or without metformin treatment, we found that metformin inhibited expression of the CSC markers Lgr5, ASCL2, EPHB3, OLFM4, BMI1, Lrig1, TERT, CD44, and CD133." (PMID 32911743, 2020).
adenoma (9 papers, 2013 to 2025). A neoplasm arising from the epithelium. "Thereby, we validated the downregulation of the stem cell markers Smoc2, Lgr5 and Olfm4, as well as the repression of several genes involved in the Wnt/β-catenin signaling and/or Notch signaling in Ap4-deficient adenomas." (PMID 30177706, 2018). "al, 2021 reported that tubular adenomas are enriched in cells referred to as ASC (Adenoma-Specific Cells) and expressed OLFM4 and LGR5." (PMID 41282138, 2025). "Especially, we identified the dysregulated stem genes including LGR5, c-Myc, and OLFM4 as the markers of adenoma, which are well preserved in HRCA-PDOs." (PMID 37667332, 2023). "Among the proteins of interest identified in adenomas were moieties associated with growth-regulating pathways; i.e. NF2 (merlin), BRCA-related protein, members of the histone 1 family and olfactomedin-4." (PMID 30995271, 2019). "The deletion of Ap4 in these tumor organoids was accompanied by lower levels of the ISC markers Smoc2, Lgr5 and Olfm4 when compared with Ap4 wild-type adenomas." (PMID 30177706, 2018). "Interestingly, we noticed that when compared to normal mucosa, both primary adenoma and CA organoids demonstrated significantly higher expression of several colon stem cell signature genes including OLFM4, LGR5, c-Myc, and CD166." (PMID 37667332, 2023). "Interestingly, OLFM4 was also detected in stromal cells such as inflammatory cells and fibroblasts and this with a higher intensity in adenoma and adenocarcinoma tissues." (PMID 28344541, 2017). "The expression of c-Myc is significantly higher in adenocarcinoma organoids than in adenoma organoids while the expression of the LGR5 and OLFM4 in adenocarcinoma organoids is extremely low." (PMID 37667332, 2023). "In adenomas, REG4+ DCS cells were enriched alongside OLFM4+ CSCs, suggesting that tDCS cells may provide trophic support to OLFM4+ stem-like populations." (PMID 41282138, 2025). "Specific paired miRNA/mRNA networks, including hsa-miR-34a-5p/SLC12A2, hsa-miR-15b-5p/SLC12A2, hsa-miR-195-5p/SLC12A2, hsa-miRNA-502-3p/OLFM4, hsa-miRNA-6807-5p/ZG16, and hsa-miRNA 3064-5p/SH3BGRL3, were identified in samples of adenoma, IMC, and CRC with the MSS phenotype." (PMID 35875068, 2022).
pancreatic cancer (9 papers, 2012 to 2025). "To investigate the prognostic value of OLFM4 expression in pancreatic cancer, we assessed the associations between OLFM4 expression levels and patient survival using Kaplan-Meier analysis with log-rank tests." (PMID 31923206, 2020). "In this study, we demonstrated that high expression of OLFM4 was significantly associated with poor prognosis in pancreatic cancer." (PMID 31923206, 2020). "In experiments using real human samples, we showed that high expression of OLFM4 was a critical independent prognostic factor and was associated with cancer survival in pancreatic cancer." (PMID 31923206, 2020). "In this study, we performed IHC analysis of OLFM4 expression using 80 pancreatic cancer tissues, instead of peripheral blood samples." (PMID 31923206, 2020). "These functions suggest that OLFM4 is involved in poor prognosis in pancreatic cancer and supported the results in our study." (PMID 31923206, 2020). "Accordingly, in this study, we first established pancreatic cancer PDXs and identified OLFM4 as a chemoresistance-related molecule in PDXs treated with anticancer drugs." (PMID 31923206, 2020). "It was confirmed that OLFM4 expression had a role in chemoresistance via an vitro experiment using pancreatic cancer cell lines." (PMID 31923206, 2020). "Correlation between OLFM4 expression and clinicopathological features in 80 cases of pancreatic cancer." (PMID 31923206, 2020). "In total, 176 pancreatic cancer samples from TCGA database were evaluated for analysis of OLFM4 expression and OS." (PMID 31923206, 2020). "Overall, our study revealed that high expression of OLFM4 was involved in chemoresistance and was an independent prognostic factor in pancreatic cancer." (PMID 31923206, 2020). "In the 80 patients with pancreatic cancer, those with OLFM4 low expression had better survival rates than patients with OLFM4 high expression (p = 0.0296)." (PMID 31923206, 2020). "In an assessment of tissue specimens from 80 patients with pancreatic cancer, Kaplan-Meier analysis showed that patients in the low OLFM4 expression group had a better survival rate than patients in the high OLFM4 expression group." (PMID 31923206, 2020). "Analysis of TCGA data also supported our results, highlighting OLFM4 expression as a prognostic factor in pancreatic cancer." (PMID 31923206, 2020). "Overall, these data showed that OLFM4 was a chemoresistance-related molecule and that OLFM4 expression was correlated with prognosis in patients with pancreatic cancer." (PMID 31923206, 2020). "In fact, antagonists of OLFM4 have been reported to inhibit the proliferation in others types of cancer cells such as human pancreatic cancer PANC-1 cells and human lung caner SBC-1 cells." (PMID 22471589, 2012). "More recently, up-regulated OLFM4 expression has been described in lung and breast, prostatic, gastric and pancreatic cancers as well as in colorectal adenomas." (PMID 22471589, 2012). "OLFM4 has been shown to be highly expressed in pancreatic cancer tissue, and reduction of OLFM4 mRNA expression by small interfering RNA (siRNA) inhibited cell proliferation, which is in accordance with our data implicating OLFM4 in regulation of cell proliferation." (PMID 35218417, 2022). "The contribution of OLFM4 to poor prognosis in pancreatic cancer may be related to the function of OLFM4." (PMID 31923206, 2020). "Importantly, high expression of OLFM4 was an independent prognostic factor for survival in patients with pancreatic cancer." (PMID 31923206, 2020). "Although we used the PDX model to study pancreatic cancer in this report, we also analyzed whether the expression of OLFM4 was observed at the protein level in specimens from patients with pancreatic cancer." (PMID 31923206, 2020). "Therefore, we examined the expression of OLFM4 protein and the relationships between OLFM4 expression and clinicopathological factors using 80 pancreatic cancer tissues from human patients." (PMID 31923206, 2020).
pancreatic cancer (continued). "Furthermore, we conducted cell viability assay for GEM-treated pancreatic cancer cell lines with both endogenous OLFM4 downregulation and upregulation." (PMID 31923206, 2020). "They concluded that OLFM4 expression in peripheral blood could be a promising tumor marker for early detection of pancreatic cancer." (PMID 31923206, 2020). "OLFM4 has also been found to promote tumor growth in pancreatic cancer, altogether suggesting that it could be an early factor of gastric tumor progression from CIM." (PMID 28441455, 2017). "In addition, we found a generally higher incidence of lung, liver, and pancreatic tumors in Olfm4+/− and Olfm4−/− mice compared with Olfm4+/+ mice at 13–24 months of age." (PMID 26581960, 2015). "Furthermore, we then analyzed whether OLFM4 was useful for the prognostic evaluation of pancreatic cancer." (PMID 31923206, 2020). "However, overall our findings indicate that OLFM4 may be a promising new prognostic marker and therapeutic target for pancreatic cancer." (PMID 31923206, 2020). "OLFM4 may be a candidate therapeutic target in pancreatic cancer." (PMID 31923206, 2020). "Therefore, OLFM4 expression may differ between pancreatic cancer and gastric or cervical cancer." (PMID 31923206, 2020). "We measured the level of OLFM4 gene expression in HeLa cells and four pancreatic cancer cell lines (PANC-1, KP2, MIA PaCa-2, and SUIT-2) by real-time RT-PCR and found that endogenous OLFM4 expression was relatively lower in PANC-1 and MIA PaCa-2 cells than in KP2 and SUIT-2 cells." (PMID 31923206, 2020).
breast carcinoma (8 papers, 2015 to 2025). "Six gene-sets were associated with spine BMFF: the top associations were breast cancer 1q21 amplicon (P = 7.08 × 10−10) and large intestine adult OLFM4 high stem cell (P = 3.11× 10−6)." (PMID 39747859, 2025). "On the other hand, reduced OLFM4 expression was significantly associated with poor prognosis in patients with gastric, colorectal and breast carcinoma amongst others." (PMID 31283789, 2019).
hepatocellular carcinoma (8 papers, 2016 to 2025). A malignant tumor that arises from hepatocytes. "Proteomic analysis of urinary exosomes from 18 hepatocellular carcinoma patients and healthy controls by mass spectrometry revealed increased expression of OLFM4, HDGF, and GDF15 in patients with hepatocellular carcinoma." (PMID 40075875, 2025). "OLFM4 is a novel prognostic predictor as well as therapeutic target for hepatocellular carcinoma." (PMID 36360315, 2022).
ovarian carcinoma (7 papers, 2016 to 2024). A malignant neoplasm originating from the surface ovarian epithelium. "ER-mediated miR-486-5p modulation of Olfactomedin 4 (OLFM4) is also implicated in ovarian cancer." (PMID 32759784, 2020). "Ovarian cancer cells transfected with miR-486-5p mimics showed decreased OLFM4 mRNA expression, and ovarian cancer cells treated with E2 showed reduced cellular miR-486-5p levels." (PMID 26871282, 2016). "Conversely, estrogen receptor signaling downregulates miR-486-5p and upregulates OLFM4 expression, slowing the development and progression of ovarian cancer." (PMID 26871282, 2016). "Scratch wound and transwell migration assays indicated that OLFM4 inhibits cell migration and invasion of ovarian cancer cells." (PMID 26871282, 2016). "Expression of OLFM4 was positively correlated with ERα expression, and estrogen (E2) treatment in ovarian cancer cells induced OLFM4 expression in an ERα-dependent manner." (PMID 26871282, 2016). "Here we demonstrated that ERα-mediated signaling regulates the expression of miR-486-5p, which targets OLFM4 in ovarian cancer." (PMID 26871282, 2016). "Next, we used ovarian cancer cells, SKOV3 and HO8910-pm, to investigate the association of OLFM4 expression with estrogen receptor signaling." (PMID 26871282, 2016). "In addition, knockdown of OLFM4 induced proliferation, invasion, and migration of ovarian cancer cells." (PMID 34122542, 2021). "Our study suggests that the role of ER signaling in ovarian cancer may be partially due to the regulation of mi-486-5p and OLFM4." (PMID 26871282, 2016). "OLFM4 knockdown enhanced proliferation, migration, and invasion by ovarian cancer cells." (PMID 26871282, 2016). "Moreover, the cell growth of papillary thyroid carcinoma is inhibited by miR-486-5p by targeting fibrillin-1, and estrogen receptor-mediated miR-486-5p could regulate the expression of OLFM4 in ovarian cancer." (PMID 32359364, 2020). "Furthermore, miR-486 might inhibit cell growth of papillary thyroid carcinoma by targeting fibrillin-1 and estrogen receptor-mediated miR-486 could regulate expression of OLFM4 in ovarian cancer." (PMID 29568407, 2018).
cervical cancer (6 papers, 2012 to 2022). A primary or metastatic malignant neoplasm involving the cervix. "In our previous studies we demonstrated that OLFM4 is also functionally associated with gynecological tumors such as cervical cancer and endometrial adenocarcinoma." (PMID 26871282, 2016). "This suggested that OLFM4 was associated with progression of cervical intraepithelial neoplasia and differentiation of cervical cancer, playing an important role in tumours of the female reproductive tract." (PMID 24495253, 2014). "In an earlier study, we found that OLFM4 expression was up-regulated in cervical epithelial carcinogenesis and linked to differentiation of cervical cancer, indicating that OLFM4 plays a role in gynecological cancer." (PMID 24495253, 2014). "Studies based on the differentiation state of gastric and cervical cancers have demonstrated that an increase in the expression of OLFM4 is correlated with tumor differentiation state." (PMID 31923206, 2020). "OLFM4 expression has been associated with progression of cervical intraepithelial neoplasia (CIN) and differentiation of cervical cancer." (PMID 26871282, 2016).